ELK1 (ETS transcription factor ELK1)
Diseases named in the same sentence as ELK1 in open-access papers (continued):
Sharing a sentence is not in itself a finding about the gene and the disease.
depression (6 papers, 2018 to 2023). "Phosphorylation of Elk1 has been also associated with some pathophysiological conditions, such as Alzheimer, Huntington, Down syndrome, synucleinopathies and depression." (PMID 30789974, 2019). "It would be also worth examining the level and/or activity of FBXO25 in people with depression and in animal models to see if it is associated with enhanced expression and activity of ELK-1." (PMID 30369870, 2018). "Elk-1 is associated with drug addiction and depression, with activation by JNK." (PMID 37146054, 2023). "Interestingly, ELK-1 has been implicated in diseases comorbid with depression." (PMID 30369870, 2018). "First, it will be interesting to examine the level and activity of ELK-1 in newborn granule cells in animal models of depression, since ELK-1 interacts with cytoskeletal proteins to reorganize dendritic morphology and synapse maturation." (PMID 30369870, 2018). "Future studies should investigate the involvement of Elk-1 in pathophysiological depression." (PMID 37146054, 2023). "Intriguingly, ELK1 plays a role in developing psychiatric disorders affecting the neural circuitry of the adult brain, and it is a prominent therapeutic target for treating depression and addiction." (PMID 36575212, 2022). "Furthermore, the authors showed that virally overexpressing ELK-1 in the dentate gyrus (DG) of mice induced depression-like behaviors." (PMID 30369870, 2018). "Since it can be speculated that the depression experienced in these diseases results from enhanced ELK-1 activity, inhibiting ELK-1 with TDE peptide might alleviate depressive symptoms in people with these diseases." (PMID 30369870, 2018). "In the experimental group, there was a non-uniform reduction in Elk-1 levels due to within-group differences in the depression and immunity levels." (PMID 37146054, 2023). "Although ELK-1's function in the cytoplasm has not been fully elucidated, there is as yet no direct evidence that its target genes are specifically involved in depression." (PMID 30369870, 2018). "Injection of blood–brain barrier-permeable TAT-DEF-ELK-1 (TDE) peptide, which disrupts ERK-mediated ELK-1 phosphorylation (activation) in the DG, improved behavioral signs in the depression models and in mice overexpressing ELK-1, without affecting basal levels of locomotion and memory." (PMID 30369870, 2018).
lung adenocarcinoma (6 papers, 2021 to 2025). A carcinoma that arises from the lung and is characterized by the presence of malignant glandular epithelial cells. "lncRNA HOXA10-AS expression was reported to be upregulated in lung adenocarcinoma, and this upregulation was induced by ELK1 overexpression." (PMID 34790276, 2021). "The Wnt/β-catenin pathway is a bridge between the functions of ELK1 and lung adenocarcinoma that can be regulated by ELK1." (PMID 34281460, 2021). "The pan-cancer analysis of the TCGA database revealed a positive correlation between ELK1 expression and the expression of MTOR in most cancer types, including lung adenocarcinoma and lung squamous carcinoma." (PMID 38397056, 2024).
neuroblastoma (6 papers, 2015 to 2024). Neuroblastoma (NB) is the most common solid, extracranial childhood tumor. "In this study, we have first aimed to identify novel targets of Elk-1 using SH-SY5Y neuroblastoma cell line in a transcriptomics approach." (PMID 33672811, 2021). "In order to identify novel target genes of Elk-1 with respect to survival in neurons, we have overexpressed Elk-1-VP16 constitutively active fusion protein in SH-SY5Y neuroblastoma cells." (PMID 33672811, 2021). "To that end, we have transfected SK-N-BE neuroblastoma and T98G GBM cell lines with Elk-1-Flag expression vector and pulled down exogenous Elk-1 using Flag-agarose beads." (PMID 33672811, 2021). "The consequences of ERK dephosphorylation could be also relevant in neuroblastoma, where ERK promotes the activity of various transcription factors such as CREB, Myc, Jun, Fos, Elk-1, Ets, Msk and Atf2." (PMID 36589747, 2022). "Activation of Elk-1 by Dr-Trks was tested in several different cell types: PC6-3 pheochromocytoma (derived from a peripheral nervous system tumor), epithelial HeLa cells, SH-SY5Y neuroblastoma, and NIH3T3 fibroblasts." (PMID 30850602, 2019). "SK-N-BE neuroblastoma cells were shown to form CD133+ tumorspheres, unlike SH-SY5Y cells, hence we have first sorted CD133− and CD133+ SK-N-BE cells and showed that expression of CD133, ELK-1, SOX2, NANOG, and POU5F1 were all significantly more in CD133+ cells than in CD133− cells." (PMID 33672811, 2021).
thyroid cancer (6 papers, 2016 to 2024). "The suppression of Elk1 inhibits thyroid cancer progression by mediating PTEN expression." (PMID 34455918, 2021). "Inhibition of ELK1 is capable of suppressing thyroid cancer progression." (PMID 31772143, 2019). "ELK1, one member of ETS factors, was also reported to interact with thyroid relevant gene promoters, presenting a regulatory role in thyroid cancer." (PMID 34281460, 2021). "In thyroid cancer, phosphorylation and activation of ETS factor ELK1 by BRAF/MAPK pathway were necessary for thyroid-specific FOXE1 recruitment to TERT promoter via direct ELK1–FOXE1 interaction and this recruitment was independent from cis-acting mutations of TERT promoter." (PMID 34221969, 2021).
nasopharyngeal carcinoma (5 papers, 2020 to 2026). A carcinoma arising from the nasopharyngeal epithelium. "Up to this day, only two studies have been conducted on Nasopharyngeal carcinoma (NPC) about ELK1’s role in disease progression." (PMID 40862737, 2025).
bladder tumors (4 papers, 2015 to 2020). "In bladder tumor samples, the expression of AR and ELK1 or phospho-ELK1 was significantly correlated." (PMID 32759680, 2020). "The underlying reasons for these findings in the expression of p-ELK1 and other transcription factors in renal pelvic tumors vs. ureteral tumors vs. bladder tumors remain undefined." (PMID 29518027, 2018). "The expression of all of these transcription factors (except ERβ), in addition to p-ELK1, was further up-regulated in bladder tumors, compared with ureteral tumors." (PMID 29518027, 2018). "The levels of p-ELK1 expression were higher in ureteral tumors than in renal pelvic tumors, as well as in bladder tumors, than in ureteral tumors." (PMID 29518027, 2018). "Our immunohistochemical staining in bladder tissue microarrays (TMAs) showed that, compared with non-neoplastic urothelium, significant increases in the expression of ELK1 and p-ELK1 were observed in bladder tumor." (PMID 26342199, 2015). "Immunohistochemistry in bladder tumor specimens showed that the levels of phospho-ELK1 (p-ELK1) expression were significantly elevated in urothelial neoplasms, compared with non-neoplastic urothelium tissues, and were also correlated with AR positivity." (PMID 26342199, 2015). "The rates of p-ELK1 positivity in the renal pelvic tumors, ureteral tumors, and bladder tumors were 40.0% (18 of 45), 56.0% (28 of 50), and 65.9% (85 of 129; shown in our previous study), respectively (renal pelvis vs. bladder: P = 0.003; ureter vs. bladder: P = 0.231)." (PMID 29518027, 2018). "More interestingly, ELK1/p-ELK1 and AR expression in bladder tumors was positively correlated." (PMID 26342199, 2015). "Finally, we used mouse xenograft models to investigate the role of ELK1 in bladder tumor outgrowth in vivo." (PMID 26342199, 2015). "In addition, phospho-ELK1 positivity in non-muscle-invasive bladder tumors was associated with a significantly higher risk of disease recurrence." (PMID 32759680, 2020). "However, as we previously suggested, differences in the anatomic location of renal pelvic/ureteral/bladder tumors and the thickness of the specimens around the tumors might have affected the immunoreactivity for p-ELK1, owing to, for instance, those in the time to complete tissue fixation." (PMID 29518027, 2018). "Our immunohistochemical staining showed significant increases in the expression of ELK1 and phospho-ELK1 (an activated form of ELK1) in bladder tumors, compared with nonneoplastic urothelial tissues." (PMID 26770009, 2015).
brain tumor (4 papers, 2021 to 2024). "Our laboratory had previously shown that Elk-1 interacted with microtubules and dynein motor protein in neurons, as well as mitotic spindle in dividing brain tumor cells; we further showed Elk-1 to colocalize and interact with mitotic kinase Aurora-A (Aur-A)." (PMID 38716144, 2024). "Among these, we have shown that genes related to pluripotency, such as Sox2, Nanog, and Oct4, were indeed regulated by Elk-1, and in the context of brain tumors, we further showed that Elk-1 overexpression in CD133+ BTIC population results in the upregulation of these genes." (PMID 33672811, 2021). "Elk-1, a member of the ternary complex factors (TCFs) within the ETS (E26 transformation-specific) domain superfamily, is a transcription factor implicated in neuroprotection, neurodegeneration, and brain tumor proliferation." (PMID 33672811, 2021). "GSEA using the patient expression profile data showed a significant enrichment of ELK1, GABP, and CREB signatures in CNS NB-FOXR2 compared to the other subtypes of pediatric brain tumors." (PMID 39220247, 2024). "On the other hand, Elk-1 was shown to regulate the CD133 gene, which is highly expressed in brain-tumor-initiating cells (BTICs) and used as a marker for separating this cancer stem cell population." (PMID 33672811, 2021).
endometrial carcinoma (4 papers, 2017 to 2026). A malignant tumor arising from the epithelium that lines the cavity of the uterine body. "In endometrial cancer, ELK1-mediated GPX4 upregulation drives chemoresistance, highlighting ferroptosis induction as a strategy to overcome treatment failure." (PMID 41824195, 2026). "In conclusion, our results suggest that GPX4 inhibits ferroptosis and promotes endometrial carcinoma progression through ELK1 transcriptional activation, and ELK1 / GPX4 axis is expected to become a new direction for the treatment of EC." (PMID 35962333, 2022). "Taken together, ELK1 could directly activate GPX4 transcription by binding to its promoter region in endometrial carcinoma." (PMID 35962333, 2022). "Considering the unique role of ELK1 in activating gene transcription related to cancer progression, we conducted an in-depth evaluation of its value in endometrial carcinoma and confirmed that ELK1 enhanced GPX4 transcription, inhibited ferroptosis, and promoted cancer progression." (PMID 35962333, 2022). "Additionally, we observe inhibition of phospho ELK1 S383 at all time points and treatments, a mechanism previously shown to mediate sorafenib-induced endometrial carcinoma apoptosis by lowering MCL1 levels." (PMID 28157711, 2017). "We then analyzed the expression of ELK1 and GPX4 in EECs and five different endometrial carcinoma cell lines." (PMID 35962333, 2022). "The results of the present study suggest that ELK1 / GPX4 axis plays an important role in the progress of EC by promoting the malignant biological behavior and inducing ferroptosis of EC cells, which provides evidence for investigating the potential therapeutic strategies of endometrial cancer." (PMID 35962333, 2022).
leukemia (4 papers, 2019 to 2025). A malignant (clonal) hematologic disorder, involving hematopoietic stem cells and characterized by the presence of primitive or atypical myeloid or lymphoid cells in the bone marrow and the blood. "Some of the modified molecules basing on ALA might be applied to the therapy of leukemias or other cancers by targeting ELK1." (PMID 38589882, 2024). "Furthermore, CRAG and ELK1 interact with promyelocytic leukaemia bodies through SUMO-interacting motifs, which is required for SRF activation." (PMID 31882856, 2019). "This suggests that ELK1 might play a significant role as an enhancer in leukemia progression." (PMID 38589882, 2024). "ALA and ELK1 are found to regulate both human granulopoiesis and erythropoiesis via RNA spliceosome, and ALA-ELK1 signal might be the target of human leukemia therapy." (PMID 38589882, 2024). "Thus, we might deliver shRNA of ELK1 to down regulate the expression of ELK1 to treat neutrophil related leukemia, which would decrease the birth of neutrophils and not affect erythrocytes differentiation." (PMID 38589882, 2024).
Obesity (4 papers, 2021 to 2024). Accumulation of substantial excess body fat.
prion disease (4 papers, 2020 to 2023). A transmissible disease that is caused by a protein that is able to induce abnormal folding of normal cellular proteins, leading to characteristic spongiform brain changes, which are associated with neuronal loss without an inflammatory response. "The genes predicted to be regulated in the “Prion disease” pathway by heroin-associated miRNAs included several transcription factors that have been demonstrated to regulate expression of proteins observed in our heroin-associated protein list, including Atp5pd (Elk1) and Uqcrfs1 (Elk1)." (PMID 38389822, 2023).
pulmonary fibrosis (4 papers, 2016 to 2024). Chronic progressive interstitial lung disorder characterized by the replacement of the lung tissue by connective tissue, leading to progressive dyspnea, respiratory failure, or right heart failure. "It was also shown that an Elk1 deficiency enhanced gene expression and exacerbated induced pulmonary fibrosis in mice." (PMID 29892964, 2018). "Crucially, we find that loss of Elk1 causes enhanced Itgb6 expression and exaggerated lung fibrosis in an in vivo model of fibrosis, whereas the GR agonist dexamethasone inhibits Itgb6 expression." (PMID 26861876, 2016). "Furthermore, loss of Elk1 in vivo increased levels of Itgb6 mRNA and collagen deposition in a bleomycin model of lung fibrosis." (PMID 26861876, 2016). "Therefore, to determine whether global loss of Elk1 was sufficient to increase Itgb6 expression in vivo and exacerbate fibrotic responses, we employed the bleomycin model of lung fibrosis." (PMID 26861876, 2016). "During the formation of pulmonary fibrosis, ELK1 transcriptionally regulates the expression of ZC3H4 to promote the silica-induced EMT program." (PMID 34970415, 2021). "Although the mechanisms regulating decreased Elk1 expression in pulmonary fibrosis are unclear, Elk1 is a target of mir-185, which is increased in lung tissue from patients suffering from rapidly progressive IPF." (PMID 26861876, 2016). "Presumably, YPEL4 and Elk1 may be possible targets in treating pulmonary fibrosis." (PMID 29892964, 2018).
squamous carcinoma (4 papers, 2015 to 2022). "In squamous cell carcinoma, the inhibitor of DNA binding 3 (Id3) induced apoptosis through an Elk-1-caspase-8-dependent pathway." (PMID 30267330, 2018).
acute myeloid leukemia (3 papers, 2024 to 2026). Acute myeloid leukemia (AML) is a group of neoplasms arising from precursor cells committed to the myeloid cell-line differentiation. "Previous reports show that ELK1 is essential for neutrophil lineage determination and ELK1 directly regulates human EVI1 gene transcription in acute myeloid leukemia." (PMID 38589882, 2024).
diabetes (3 papers, 2013 to 2022). "In the neural retina, diabetes-associated decrease of miR-150 promotes inflammation and apoptosis of photoreceptors via Elk1, which contribute to the microvascular degeneration in DR." (PMID 36292956, 2022). "The results imply that knocking down Elk1 can potentially alleviate diabetes‐associated inflammation in retinal photoreceptors." (PMID 34704358, 2021). "Therefore, in addition to dampening the expression of ELK1, blocking the translocation of pELK1T417 to the nucleus may be more critical to mitigate diabetes-associated apoptosis in photoreceptors." (PMID 36292956, 2022). "Therefore, Elk1 might be a new target for future therapeutics to treat diabetes‐associated inflammation and potentially prevent the development of DR." (PMID 34704358, 2021). "Since inhibiting NFĸB P65 alleviates high glucose‐induced apoptosis in endothelial cells, knockdown of Elk1 could mitigate diabetes‐induced damage to the retinal vasculature." (PMID 34704358, 2021). "The presence of MAPK1/ELK1/CREBBP axis in the core subnetwork and its direct crosstalk to the insulin pathway is consistent with experimental observations that link insulin signaling and diabetes risk to the regulation of learning and formation of long-term memory." (PMID 23885764, 2013).
diabetic nephropathy (3 papers, 2022 to 2025). "Besides, since ELK1 has been shown to regulate inflammation in acute lung injury and diabetic nephropathy 46, 47, it is plausible that ELK1 may also be involved in RTEC death and interstitial inflammation." (PMID 40959284, 2025). "Notably, SIRT7 and ELK1 mutually inhibit each other at the DAPK3 promoter; thus, forced SIRT7 overexpression may kill the hyperglycemic memory of the ELK1-DAPK3 axis and alleviate diabetic nephropathy." (PMID 37676263, 2024).
Insulin resistance (3 papers, 2013 to 2025). Increased resistance towards insulin, that is, diminished effectiveness of insulin in reducing blood glucose levels. "The connection between AKT and MAPK1 has been shown since both signals are a mechanism for insulin resistance in adipocytes through the nuclear factor Elk1." (PMID 39484291, 2024). "Future studies should investigate whether IPMK deletion directly impacts Elk-1 activity in skeletal muscle and how this contributes to the metabolic phenotypes observed, including insulin resistance and altered lipid metabolism." (PMID 40141045, 2025).
insulinoma (3 papers, 2013 to 2025). "ELK1 has also been reported as an upregulated transcription factor is a PaCa subtype characterized by insulin overproduction, namely insulinoma." (PMID 40862737, 2025). "In insulinoma cell lines, activation of ELK1 via MAPK signaling has been found to be a result of B-Raf activation by glucose." (PMID 40862737, 2025). "In this study, we investigated the effects of Elk-1 on COX-2 gene expression and GSIS function in INS-1 rat insulinoma cells and explored whether Elk-1 regulates COX-2 expression through its potential binding site in COX-2 promoter." (PMID 23818898, 2013).
laryngeal squamous cell carcinoma (3 papers, 2021 to 2025). A squamous cell carcinoma that arises from the larynx. "CircPPFIA1 enhances the metastatic potential of laryngeal squamous cell carcinoma via miR-340-3p/ELK1." (PMID 36224588, 2022). "In laryngeal squamous cell carcinoma (LSCC), miR-340-3p was identified as suppressor of ELK1, inhibiting its transcription by binding near on ELK1 mRNA." (PMID 40862737, 2025).
Lewy body disease (3 papers, 2010 to 2023). "The co-localization of T417+ Elk-1 with Lewy bodies is present in tissue from other variants of Lewy Body Disease." (PMID 20126313, 2010). "We first tested whether Elk-1 protein can co-localize with Lewy bodies in brain tissue from patients with Lewy Body Disease." (PMID 20126313, 2010).
triple-negative breast carcinoma (3 papers, 2016 to 2020). An invasive breast carcinoma which is negative for expression of estrogen receptor (ER), progesterone receptor (PR), and human epidermal growth factor receptor 2 (HER2). "The acidic domain of MZF1 is involved in its association with Elk1 in triple negative breast cancer." (PMID 31963147, 2020). "Recently, the MZF1/Elk-1 complex has been identified as mediator of protein kinase C alpha (PKCα) expression in triple-negative breast cancer, which induces cell migration and invasion of triple negative breast cancer cells and poor outcome." (PMID 28435519, 2017). "In triple-negative breast cancer cells, MZF1 activation can maintain the mesenchymal phenotype by interacting with Elk1 at the promoter region of IGF1R." (PMID 31963147, 2020).